PRNP (prion protein (Kanno blood group))
Description:
Its primary physiological function is unclear. May play a role in neuronal development and synaptic plasticity. May be required for neuronal myelin sheath maintenance. May promote myelin homeostasis through acting as an agonist for ADGRG6 receptor. May play a role in iron uptake and iron homeostasis. Soluble oligomers are toxic to cultured neuroblastoma cells and induce apoptosis (in vitro) (By similarity). Association with GPC1 (via its heparan sulfate chains) targets PRNP to lipid rafts. Also provides Cu(2+) or Zn(2+) for the ascorbate-mediated GPC1 deaminase degradation of its heparan sulfate side chains (By similarity).
Synonyms: PrP; CD230; ALTPRP; PRIP; ASCR; CJD; GSS; KURU; PrP27-30; PrP33-35C; PrPc; p27-30
Tractability: Small molecule: it has a binding pocket of medium quality. Antibody: its Gene Ontology location is reachable by antibodies, with high confidence; UniProt places it where antibodies can reach, with medium confidence; UniProt predicts a signal peptide or a membrane-spanning region. PROTAC: ubiquitination databases record sites on it; its protein half-life has been measured; a small molecule that binds it is known.
Target class: Surface antigen
Gene: Protein-coding gene on chromosome 20 (4,685,730 to 4,701,590, forward strand). Ensembl gene ENSG00000171867.
Subcellular location: Cell membrane; Golgi apparatus; Mitochondrion outer membrane
Subcellular location (Human Protein Atlas): Cytosol; Nuclear membrane; Vesicles
Pathways (Reactome):
Developmental Biology: NCAM1 interactions
Protein localization: Insertion of tail-anchored proteins into the endoplasmic reticulum membrane
Gene Ontology:
Molecular function: amyloid-beta binding; copper ion binding; cuprous ion binding; identical protein binding; microtubule binding; molecular adaptor activity; molecular condensate scaffold activity; protein binding; protein-containing complex binding; tubulin binding; type 8 metabotropic glutamate receptor binding; aspartic-type endopeptidase inhibitor activity; glycosaminoglycan binding; protease binding; signaling receptor activity; type 5 metabotropic glutamate receptor binding; ATP-dependent protein binding; cupric ion binding; lamin binding; metal ion binding; molecular function activator activity; protein-folding chaperone binding; transmembrane transporter binding
Biological process: cellular response to amyloid-beta; cellular response to copper ion; intracellular signal transduction; positive regulation of calcium-mediated signaling; positive regulation of glutamate receptor signaling pathway; positive regulation of neuron apoptotic process; protein destabilization; dendritic spine maintenance; intracellular copper ion homeostasis; learning or memory; long-term memory; negative regulation of activated T cell proliferation; negative regulation of amyloid precursor protein catabolic process; negative regulation of amyloid-beta formation; negative regulation of calcineurin-NFAT signaling cascade; negative regulation of dendritic spine maintenance; negative regulation of interleukin-17 production; negative regulation of interleukin-2 production; negative regulation of protein processing; negative regulation of T cell receptor signaling pathway; negative regulation of transcription by RNA polymerase II; negative regulation of type II interferon production; neuron projection maintenance; positive regulation of protein targeting to membrane; regulation of calcium ion import across plasma membrane; and 9 more
Cellular component: cell surface; dendrite; extracellular exosome; inclusion body; membrane raft; plasma membrane; cytoplasm; cytosol; endoplasmic reticulum; external side of plasma membrane; extrinsic component of membrane; Golgi apparatus; postsynapse; postsynaptic density; membrane; terminal bouton
Genetic constraint (gnomAD): Loss-of-function variants: 15 observed, 22.29 expected, observed/expected ratio (o/e) 0.67, 90% interval 0.45 to 1.04. The upper end of that interval is the gene's LOEUF score, 1.04, which puts it in group 4 of 6, group 1 being the genes least tolerant of losing a copy. Missense variants: 285 observed, 360.02 expected, observed/expected ratio (o/e) 0.79, 90% interval 0.72 to 0.87. Synonymous variants: 121 observed, 128.78 expected, observed/expected ratio (o/e) 0.94, 90% interval 0.81 to 1.09.
Homologues: Orthologues: chimpanzee PRNP (99% identical), macaque PRNP (96% identical), mouse Prnp (90% identical), rat Prnp (90% identical), pig PRNP (89% identical), rabbit PRNP (89% identical), dog PRNP (87% identical), guinea pig PRNP (83% identical), tropical clawed frog prnp (28% identical).
Diseases named in the same sentence as PRNP in open-access papers:
PRNP is named in the same sentence as 241 diseases in open-access papers, as found by Europe PMC text mining. Sharing a sentence is not in itself a finding about the gene and the disease. The quoted sentences say what the papers report.
prion disease (650 papers, 2004 to 2026). A transmissible disease that is caused by a protein that is able to induce abnormal folding of normal cellular proteins, leading to characteristic spongiform brain changes, which are associated with neuronal loss without an inflammatory response. "At the host genomic level, polymorphisms in the PRNP gene constitute primary determinants of prion disease susceptibility, incubation period, and clinicopathological manifestations." (PMID 41347242, 2025). "Over 50 pathogenic PRNP mutations have been reported worldwide, underlying familial prion disease variants." (PMID 41347242, 2025). "An asymptomatic cohort study participant under age 50 harbouring a PRNP mutation exhibited a spike in NfL concentration in both plasma and CSF unaccompanied by any change in other fluid biomarkers of prion disease." (PMID 40417399, 2025). "Inherited prion diseases (IPDs) are phenotypically diverse neurodegenerative conditions caused by mutations in the prion protein gene (PRNP)." (PMID 40156621, 2025). "In fact, due to the outstanding conservation found among mammalian PRNP sequences, it is quite challenging to ascertain the molecular determinants that drive the differences in prion disease susceptibility among mammalian species." (PMID 40561181, 2025). "Prion disease is a fatal neurodegenerative disease caused by the misfolding of prion protein (PrP) encoded by the PRNP gene." (PMID 39810005, 2025). "This seems plausible because VPSPr is several times rarer than genetic prion disease caused by highly penetrant PRNP coding variants, which collectively are estimated to have a genetic prevalence of ~1 in 50,000 people." (PMID 39711705, 2025). "Prion diseases are neurodegenerative conditions caused by the aberrantly folded isoform of prion protein (PrP Sc), with polymorphisms in the PRNP gene." (PMID 41142443, 2025). "We explored the relationship between positive family history and OR for known causal PRNP variants in genetic prion disease." (PMID 39711705, 2025). "Efforts to model heritable prion diseases in transgenic (Tg) mice expressing PRNP mutations that are strongly linked to genetic forms of Creutzfeldt–Jakob disease (gCJD) in humans have met with only limited success." (PMID 40522345, 2025). "Prion diseases are associated with rare mutations of the PRNP gene (genetic forms) or rare transmission of the prion protein between humans and mammals (acquired forms)." (PMID 39337449, 2024). "Prion diseases can be associated with mutations in the prion protein gene (PRNP), induced by the exposure to prion-contaminated materials, or arise sporadically." (PMID 39656691, 2024). "Prion disease is a rapidly fatal neurodegenerative disease caused by the templated misfolding of the prion protein, PrP, encoded by the prion protein gene (PRNP in humans)." (PMID 39002681, 2024). "The polymorphism of the PRNP gene plays a great role in the susceptibility of animals to prion protein diseases." (PMID 38355406, 2024). "Vallabh, a carrier of PRNP mutation, has proposed a novel preventive treatment approach targeting individuals diagnosed early with hereditary prion diseases." (PMID 38500676, 2024). "Some cases of human prion diseases are linked to PRNP stop mutations causing expression of pathogenic C-terminally truncated (and hence anchorless) PrP versions, which form large extracellular and often vessel-associated deposits." (PMID 38980441, 2024). "A polymorphism at codon 129 (c129) within the prion protein gene (PRNP) significantly impacts both susceptibility to and the clinical characteristics of human prion diseases." (PMID 38396996, 2024). "About 15% of prion disease cases are genetic; caused by autosomal dominant mutations within the PRNP gene encoding the prion protein (PrP)." (PMID 36656833, 2023). "Inherited mutations in the PRNP gene are responsible for some prion diseases, as in the case of Fatal Familial Insomnia (FFI) and Gerstmann-Sträussler-Scheinker disease (GSS)." (PMID 36915214, 2023).
prion disease (continued). "The N-terminus of the PRNP gene normally contains a 5-octapeptide repeat (R1-R2-R2-R3-R4), and insertions at this locus can cause hereditary prion diseases." (PMID 36977684, 2023). "Since prion diseases are associated with protein stability, further validation of the relationship between the synonymous SNP of the leporine PRNP gene and the structural stability of leporine PrP at the molecular level is highly desirable." (PMID 37808111, 2023). "The incidence of prion disease is estimated to be about 0.2 per 100,000 annually, with genetic prion disease related to PRNP mutations accounting for 10% of this number." (PMID 38132285, 2023). "In Japan, prion disease surveillance began in 1999 to identify all patients with prion diseases, and prion-related protein analyses using cerebrospinal fluid (CSF) and PRNP gene analysis have continued as important diagnostic tests." (PMID 36977684, 2023). "Fatal familial insomnia (FFI) belongs to the group of genetic prion diseases and is caused by an autosomal-dominant inherited point mutation, D178N, in PRNP." (PMID 37626863, 2023). "Fatal familial insomnia (FFI) is a very rare and untreatable inherited neurodegenerative prion disease caused by a PRNP mutation." (PMID 37626863, 2023). "Recent studies have reported that the K200 mutation of the PRNP gene has shown high penetrance and was confirmed as a causal factor of prion diseases using a transgenic mouse model." (PMID 37834279, 2023). "Gerstmann-Sträussler-Scheinker syndrome (GSS) is a rare genetic prion disease caused by a mutation in the prion protein (PRNP) gene." (PMID 37602242, 2023). "Recent GWAS studies successfully contributed to the identification of additional genetic risk factors for prion disease other than PRNP." (PMID 37626863, 2023). "The prion protein gene (PRNP) encodes the host-encoded cellular prion protein (PrPC), which plays an important role in prion disease and prevents the development of the disease or the transmission of the disease when PrPC is absent." (PMID 38066978, 2023). "Worldwide, 10–15% human prion disease are genetic and inherited, due to the special mutations or insertions in PRNP gene." (PMID 37962387, 2023). "About 20 different types of PRNP mutations have been reported in Chinese patients with prion diseases, among them T188K genetic CJD (gCJD), D178N FFI and E200K gCJD are the most frequent." (PMID 37962387, 2023). "Regarding the gene PRNP, several variants have been suggested to play a role in other neurodegenerative disorders besides prion disease." (PMID 35650585, 2022). "Inherited prion diseases (IPD) are a set of rare neurodegenerative diseases that are always caused by mutation of the prion protein gene (PRNP)." (PMID 35754056, 2022). "As the PRNP E200K mutation causes prion disease, we additionally assessed prion seeding activity as a biochemical indicator of PrPD." (PMID 36138047, 2022). "Predictive genetic testing is available to individuals with a family history of genetic prion disease, defined as a family member with a PRNP mutation or two or more family members diagnosed with prion disease." (PMID 36277922, 2022). "The intronic variant in PRNP is also referred to with the ID rs6037932, this variant was used in a phylogenetic study about founder effect in another prion disease (FFI) in 2008." (PMID 36517866, 2022). "In familial forms of prion diseases, mutations in the PRNP gene result in an increased propensity of PrPC adopting the PrPSc conformation compared to wild type PrPC." (PMID 35337037, 2022). "Prion diseases are classified into sporadic (85%), genetic (10–15%) (due to mutations in the prion protein gene (PRNP)) and acquired (exceptional) forms." (PMID 35454316, 2022). "The prion protein gene (PRNP) encodes for the cellular prion protein, which is the biological substrate for prion disease transmission and neurotoxicity." (PMID 36277922, 2022).
prion disease (continued). "Genetic Creutzfeldt–Jakob disease (gCJD) is a prion disease caused by mutations in the prion protein gene (PRNP)." (PMID 35130121, 2022). "The prion strain variation and polymorphism in the codon 129 of the PRNP gene are the major factors responsible for the clinicopathological phenotype and the susceptibility of an individual to develop prion disease." (PMID 35335141, 2022). "RT-QuIC performance in identifying slowly progressive inherited prion diseases including Gerstmann-Straussler-Scheinker syndrome IPDs and in fatal familial insomnia caused by D178N PRNP mutation appears less good." (PMID 35813946, 2022). "All the genetic forms of prion disease are linked to PRNP mutations and include point mutations, octapeptide repeat insertions and deletions." (PMID 35454316, 2022). "PRNP polymorphisms and pathogenic variants play a large role in the frequency, age at onset, and clinicopathologic phenotype of prion diseases." (PMID 36277922, 2022). "T188K gCJD is the second most common observed genetic prion disease in China after fatal familial insomnia caused by the PRNP D178N mutation but is rarely reported in other countries." (PMID 35130121, 2022). "Sheep pruritus is an infectious and incurable prion disease which is caused by variant prion protein (PRNP)." (PMID 35327291, 2022). "PRNP can contain pathogenic variants/mutations that result in various forms of genetic prion disease that differ in penetrance, clinical phenomenology, age at onset, disease duration, and diagnostic test results." (PMID 36277922, 2022). "Genetic variation in PRNP, the gene encoding cellular PrP, has long been recognized as an important factor in prion-disease modulation in both animals and humans." (PMID 34823556, 2021). "The pathologically misfolded isoform of PRNP (PrPSc) causes prion diseases (e.g., CJD), and was further shown to be involved in AD." (PMID 34959983, 2021). "Although miRNA mimics have been used in vitro to validate putative prion mRNA-targeting miRNAs, to our knowledge, no replacement approaches have been tested in vitro or in vivo aiming to normalize deregulated miRNAs in (PRNP-linked) prion diseases to date." (PMID 34209482, 2021). "In this report, we describe the clinical, neuropathological, and biochemical phenotype of genetic prion disease associated with a biallelic R136S substitution in the PRNP gene in a Spanish family." (PMID 34663460, 2021). "Of the 232 vCJD cases who have undergone full genetic analysis, all but a single case has occurred in individuals homozygous for methionine (MM) at codon 129 on PRNP, a recognised risk factor for human prion diseases." (PMID 34832569, 2021). "The existence of PRNP mutations that segregate with familial prion diseases raises the critical question of these mutations' pathogenic role, including their effect on disease phenotype and the generation of strain-specific properties." (PMID 34324063, 2021). "We describe the clinical and neuropathological data of inherited early-onset prion disease caused by the rare PRNP homozygous mutation R136S." (PMID 34663460, 2021). "The prion protein gene (PRNP), highly conserved across mammals, is considered the major genetic determinant of susceptibility to prion diseases." (PMID 33801117, 2021). "Forty-two different mutations in the PrP gene (PRNP) were identified to cause a variety of genetic prion diseases, including genetic Creutzfeldt-Jakob disease (CJD), Gerstmann-Sträussler-Scheinker disease, and fatal familial insomnia." (PMID 34516876, 2021). "More than 40 pathogenic heterozygous PRNP mutations causing inherited prion diseases have been identified to date." (PMID 34663460, 2021). "Any future treatment aimed to prevent prion disease cannot prescind from the identification and longitudinal evaluation of pre-symptomatic PRNP mutation carriers." (PMID 33776643, 2021).